WWOX (WW domain containing oxidoreductase)
Diseases named in the same sentence as WWOX in open-access papers (continued):
Sharing a sentence is not in itself a finding about the gene and the disease.
cancer (continued). "The novel pleiotropic gene WWOX is a cancer suppressor gene that could induce apoptosis and inhibit growth in various cancers." (PMID 38259487, 2023). "Finally, stimulating the membrane HYAL-2/WWOX complex with HYAL-2 antibody or sonicated hyaluronan (HAson) leads to Z cell activation for killing cancer cells in vivo and in vitro." (PMID 35883580, 2022). "Notably, the stronger the binding of WWOX with intracellular protein partners, the better the cancer suppression." (PMID 36498839, 2022). "In cancer, focal deletions are often associated with CFS; in a pan-cancer analysis of 4934 cases, 70 recurrent focal deletions were reported, of which 22 were found in large genes and several genes known from CFS regions (FHIT, WWOX, PDE4D, PARK2)." (PMID 35563471, 2022). "Importantly, WWOX7-21 peptide strengthens the binding of WWOX with intracellular proteins for blocking cancer and AD progression." (PMID 35883580, 2022). "Whether the HYAL-2/WWOX/SMAD4 signaling limits cancer and neurodegeneration in a balanced manner is unknown." (PMID 35883580, 2022). "The observations indicate that WWOX with S14 phosphorylation is pro-survival for cancer cells." (PMID 35883580, 2022). "Additionally, it has been suggested that the phosphorylation of WWOX on its serine 14 facilitates cancer progression." (PMID 33946771, 2021). "The second most fragile gene, WWOX, became the subject of our research, since in BLCA patients, the frequency of chromosome breakage at FRA16D increases when patients have a smoking habit, which is a risk factor for that cancer." (PMID 34204827, 2021). "The role of the WWOX-Ezrin complex in cancer has yet to be determined." (PMID 33946771, 2021). "Most strikingly, cancer-regulated protein aggregation in the brain is blocked by WWOX." (PMID 34359949, 2021). "Together, these data suggested a protective role for WWOX in the promotion of cell death in response to increased ROS levels, which could correlate with altered metabolism that is observed in cancer." (PMID 34210081, 2021). "Mutations inactivating both WWOX alleles have not been found in cancer; however, the loss of one allele is sufficient to affect its normal biological function." (PMID 33691672, 2021). "Homozygous deletions of WWOX have also been detected in different cancer cells." (PMID 33946771, 2021). "However, in mice receiving both Zfra4-10 and WWOX7-21 peptides, WWOX had reduced binding with the target proteins down to a basal level, and cancer growth was significantly increased." (PMID 32764489, 2020). "We investigated whether synthetic Zfra4-10 or WWOX7-21 peptide-mediated cancer suppression occurs via the Hyal-2/WWOX/SMAD4 signaling for cytotoxic memory Z cell activation in the spleen." (PMID 32764489, 2020). "TMEM207 abolishes the binding of WWOX with HIF-1α to enhance cancer growth." (PMID 32764489, 2020). "For example, WWOX regulates the function of HIF-1α in promoting cancer progression." (PMID 32764489, 2020). "In addition to the homozygous deletion of the WWOX gene its decreased or aberrant expression has also been reported in multiple human cancers 13-16." (PMID 32368285, 2020).
cancer (continued). "Indeed, antibodies against pY33-WWOX and Zfra4-10 peptide are potent in blocking cancer growth, suggesting that the Hyal-2/WWOX signaling is functioning in the anticancer response." (PMID 32764489, 2020). "We investigated whether Zfra and WWOX peptides functionally counteract each other and thereby fail to suppress cancer growth in vivo." (PMID 32764489, 2020). "Although the functional significance of the binding is unknown, an enhanced binding of WWOX with its partners is critical in blocking cancer cell growth in vivo." (PMID 32764489, 2020). "High levels of hyaluronidases suppress WWOX expression and increase cancer metastasis." (PMID 31123603, 2019). "However, when S14 is phosphorylated and Y33 is de-phosphorylated in WWOX, pS14-WWOX supports cancer growth." (PMID 31752354, 2019). "We examined whether WWOX peptides adhere to a specific protein(s) on cancer cell surface and thereby signal for cancer cell survival or death." (PMID 31752354, 2019). "WWOX-mediated cancer suppression has recently been established in Drosophila." (PMID 31752354, 2019). "Here, we investigated whether membrane WWOX receives extracellular signals via surface-exposed epitopes, especially at the S14 area, that signals for cancer growth suppression and prevention." (PMID 31752354, 2019). "We investigated the in vivo effects of WWOX peptides in controlling cancer growth." (PMID 31752354, 2019). "For example, WWOX7-21 peptide may physically bind the membrane Hyal-2/WWOX complex to undergo nuclear relocation, together with Smad4, for blocking cancer cell growth." (PMID 31752354, 2019). "Suppression of TIAF1 by siRNA enhances cancer cell growth and abolishes WWOX-mediated apoptosis." (PMID 31315632, 2019). "Although WWOX is considered as a tumor suppressor protein, WWOX-deficient human newborns do not spontaneously develop cancer." (PMID 31752354, 2019). "Restoration of WWOX expression in several types of cancer cells induced apoptosis." (PMID 30285739, 2018). "The authors suggest that the loss of the signal pathway in which WWOX is involved contributes to lymph node metastasis by allowing detached cancer cells to survive without contact with the basal membrane." (PMID 30211123, 2018). "Thus, WWOX suppressor activity relies on its binding capacities to known cancer-related proteins such as p73, deltaNp63, AP2γ, c-jun, Erbb4, c-Met, RUNX2, and Dvl-2." (PMID 30285739, 2018). "Nevertheless, the functional association of WWOX-HIF1α has not been demonstrated in a cancer mouse model." (PMID 29724996, 2018). "We propose that this inhibitory mechanism of TMEM207 to WWOX might lead to carcinogenesis if cancer cells continue to express the WWOX protein." (PMID 30214895, 2018). "Combined together with the finding of co-immunoprecipitation assay, which showed the binding of TMEM207 to WWOX as its PPxY motif dependent manner, pathobiological link of TMEM207 and WWOX may be occurred in various cancer cells." (PMID 30214895, 2018). "In addition, we elucidated a novel mechanism by which evodiamine activates WWOX to exert an anti-cancer activity." (PMID 28708106, 2017). "Decreased expression or genetic alteration of WWOX has been detected in various malignant tumors." (PMID 28426730, 2017). "Somatic and germline mutations of WWOX, including loss of heterozygosis (LOH), homozygous deletions and chromosomal translocations, has been reported to evolve in carcinogenesis and development in several types of cancers." (PMID 26910372, 2016). "Most recently, WWOX-mediated suppression of cancer cell growth has been established in Drosophila." (PMID 27999774, 2016).
cancer (continued). "Altered expression of WWOX has been reported for many different cancer cell types." (PMID 26302329, 2015). "It has been shown that dys-regulation of WWOX could contribute to genomic instability, cancer progression and therapy resistance." (PMID 25708809, 2015). "The prevalence of one phenotype over the other could likely be related to context (e.g. tissue type or occurrence of other mutations) though more studies should be required to better understand the role of WWOX in biology and cancer." (PMID 26256646, 2015). "Likewise, FHIT and WWOX deletions within fragile sites FRA3B (most frequently expressed) and FRA16D, respectively, have been observed in many cancers." (PMID 26337081, 2015). "We now hypothesise that, through regulation of reactive oxygen species, WWOX constitutes a link between alterations in cellular metabolism observed in cancer cells and their ability to evade normal cell death pathways." (PMID 26302329, 2015). "WWOX and FHIT are tumor suppressor genes that are mutated in a wide range of cancers and could result in greater genomic instability given their roles in detecting genotoxic stress and regulation of the cellular response to genomic damage." (PMID 24454681, 2014). "The aim of this study was to characterize how WWOX may be involved in colon cancerogenesis or cancer progression and how it influences the basic cancer cell features (i.e. viability, proliferation and apoptosis) and modifies cell expression profile." (PMID 24938873, 2014). "The function of WWOX in the suppression of cancerogenesis has been confirmed previously in cancers of hormone-related tissues, including breast, ovary and prostate, but also in cancers from gastrointestinal tract, such as gastric, oesophageal, pancreatic and liver tissue." (PMID 24938873, 2014). "During cancer progression, the expression profiles for WWOX and TIAF1 appear similarly." (PMID 27234387, 2013). "Moreover, a number of authors have shown that the suppressed transcription of WWOX and FHIT is associated with the more advanced stages in various types of cancer, including breast, non-small cell lung and ovarian cancers." (PMID 24137446, 2013). "Binding of WWOX with LMP2A may render functional inactivation of WWOX and thereby enhances cancer growth and invasion." (PMID 27234396, 2013). "WWOX protein expression is frequently downregulated in invasive cancer cell types." (PMID 27234396, 2013). "Susceptibility of FRA16D to carcinogen-induced damage may explain the high frequency of WWOX gene alterations in HCC, a cancer closely associated with exposure to chemical carcinogens and infection with oncogenic viruses." (PMID 15266310, 2004). "Although it is known that WWOX loss promotes cisplatin resistance through effects on the choice of a DNA repair pathway that contributes to enhanced mutagenesis, the downstream expression changes in resistant cancer cells have not been fully explored." (PMID 39473747, 2024). "Thus, accumulating reports demonstrating the potential role of WWOX in many types of metabolic disorders and metabolic rearrangements in cancer opens the possibility for its therapeutic implementation while also contributing to our understanding on a basic science level." (PMID 36271927, 2022). "It was found that both WWOX and AP-2α hinder cancer progression and may act synergistically." (PMID 34204827, 2021). "We investigated whether WWOX peptides affect cancer cell metastasis and immune cell expansion." (PMID 31752354, 2019).
cancer (continued). "Furthermore, to realize correlation between the mRNA, protein level of WWOX and rs11545028 polymorphism, quantitative real time-PCR (qPCR) and Immunohistochemical (IHC) staining were used to analyze WWOX mRNA and protein expression in cancer tissue of 34 and 51 OSCC patients, respectively." (PMID 27655721, 2016). "In addition, alterations to ROS levels would occur as a consequence of cancer cells shifting their metabolism from oxidative phosphorylation to a more glycolytic Warburg-based metabolism and we have previously shown that WWOX is both responsive to, and contributes to aerobic metabolism." (PMID 26302329, 2015). "However, taking under consideration cell line features, our observations suggest that increased expression of WWOX may transform HT29 cancer cells into a more normal colon epithelium phenotype." (PMID 24938873, 2014). "Thus, cancer cells with defect in their WWOX gene would probably resist to etoposide chemotherapy." (PMID 22615609, 2010). "Downregulation or absence of WWOX mRNA expression in various types of cancer can be attributed to mutation, homozygous deletion, chromosomal translocations within or near the WWOX locus, hypermethylation of the promoter region or alterations in transcriptional control." (PMID 15266310, 2004). "We established that the WWOX/HIF1A ratio orchestrates tumour immune responses, fundamentally shaping immune evasion, inflammation, and immune cell infiltration across cancers." (PMID 41007296, 2025). "The WW domain-containing oxidoreductase (WWOX) gene maps to chromosome 16q23.1–23.2 and spans the second most common chromosomal fragile site (FRA16D) frequently altered in cancer." (PMID 37974179, 2023). "Considering downstream regulation, WWOX inhibited the expression of RUNX2 and its target gene MMP9, reducing cancer invasiveness." (PMID 36979157, 2023). "The stronger the binding, the weaker the cancer growth, suggesting that Zfra4-10 or WWOX7-21 peptide-induced HYAL-2/WWOX/SMAD4 signaling is involved in the increased binding of WWOX with its partners." (PMID 35883580, 2022). "A significant positive correlation between WWOX and the mRNA levels of the isocitrate dehydrogenase family member IDH1 was also observed in many human cancer cell lines." (PMID 36271927, 2022). "The WWOX gene encompasses the FRA16D fragile region, which frequently undergoes chromosomal breaks and rearrangements in cancers." (PMID 34948746, 2021). "Only a few papers clarified that processes such as promoter methylation or LOH leads to downregulation of WWOX expression in BLCA patients and mentioned the connection with a more aggressive cancer phenotype." (PMID 33691672, 2021). "miRNAs play direct or indirect roles in regulating oncogenes (KRAS), tumor suppressor genes (FHIT, WWOX), and immune-related gene (TLR8), which ultimately promote cancer cell growth and dissemination." (PMID 34470640, 2021). "Thus, WWOX may act as an adapter protein with pleiotropic functions resulting from a network of interactions regulating the transcription, the localization, or the degradation of key cancer-related proteins." (PMID 33946771, 2021). "In contrast to WWOX and DVL2, expression rates of DVL1 and DVL3 were higher in cancer cell lines compared to normal 26-28." (PMID 32368285, 2020). "The WW domain-containing oxidoreductase (WWOX) tumor suppressor gene is frequently lost in a variety of solid and hematopoietic malignancies in humans." (PMID 33129329, 2020). "This raises the strong scenario that both peptides drive a common signal pathway, which is Hyal-2/WWOX/SMAD4, to limit cancer growth." (PMID 32764489, 2020).
cancer (continued). "Therefore, impaired WWOX function may participate in the “Warburg effect” through HIF1α stabilization, which increases the expression of Glut1 and other aerobic glycolytic metabolism-related molecules in cancer invasion microenvironments." (PMID 30214895, 2018). "Our results suggest that VOPP1 promotes cancer by inhibiting WWOX-dependent apoptosis; however, we cannot exclude the possibility that VOPP1 acts on cancer by impairing other WWOX functions." (PMID 30285739, 2018). "Deletions in many of our hotspot genes (e.g., NRXN1, PDE4D, WWOX, LSAMP, and NEGR1) are also found in numerous cancers where they likely represent the effects of perturbed replication and transcription." (PMID 25373142, 2015). "WWOX (WW domain containing oxidoreductase) spans one of the two most active fragile sites in the human genome (FRA16D, human chromosome 16q23) and is disrupted frequently in several human cancers." (PMID 25957863, 2015). "Recurrent alterations have been identified in FRA3B and FRA16D in several cancer types, leading to further investigation of the FHIT and WWOX genes, respectively, in mouse models (see K. Huebner and R. Aqeilan chapters in this issue)." (PMID 25238782, 2014). "Our study aimed to investigate whether the WWOX/HIF1A ratio affects the overall survival of patients, whether it allows for the identification of differences between cancer subtypes, and through which pathways it exerts its regulatory effects." (PMID 41007296, 2025). "In addition to its established roles in metabolism and signalling, our analyses identified through our analyses that the WWOX/HIF1A expression ratio emerges as a pivotal determinant of genomic integrity and DNA repair fidelity across multiple cancer types." (PMID 41007296, 2025). "Additionally, studies have shown that WWOX engages with SMAD3 and BMP2 to regulate TGFβ/BMP signaling, suppressing epithelial–mesenchymal transition (EMT) and cancer stem cell phenotypes, thereby inhibiting the progression of pancreatic ductal adenocarcinoma." (PMID 41228229, 2025). "The WWOX gene (WW domain-containing oxidoreductase) is located in the fragile region FRA16D on chromosome 16q23.3–24.1, an area prone to genetic rearrangements in different types of cancer." (PMID 39796213, 2025). "Human WWOX gene resides at the chromosomal fragile site FRA16D that exhibits an increased frequency of breakage upon replication stress and is preferentially unstable during cancer progression." (PMID 37897534, 2023). "The tumor suppressor gene WWOX is localized in an unstable chromosomal region and its expression is decreased or absent in several types of cancer." (PMID 37248434, 2023). "Interestingly, WWOX, the sense gene of WWOX-AS1, has been confirmed to exert an anticancer role in various cancers and is found to be downregulated in HCC." (PMID 37240232, 2023). "In addition, we have identified large genes residing in common fragile sites to be significantly affected by deletions and contributing to cancer development, including CSMD1, WWOX and FHIT." (PMID 36726722, 2022). "In this perspective review article, we detail the molecular action of WWOX in the HYAL-2/WWOX/SMAD4 signaling for biological effects, and discuss WWOX phosphorylation forms in interacting with binding partners, leading to suppression of cancer growth and retardation of AD progression." (PMID 35883580, 2022). "Although all the designed drugs utilize the HYAL-2/WWOX/SMAD4 signaling to control cancer growth, it is necessary to compare the efficacy of HAson8, Zfra4-10, WWOX7-21 and other available drugs in treating cancer in vivo." (PMID 35883580, 2022).